CBL (Cbl proto-oncogene)
Diseases named in the same sentence as CBL in open-access papers (continued):
Sharing a sentence is not in itself a finding about the gene and the disease.
myeloid neoplasm (27 papers, 2010 to 2025). Proliferation of myeloid cells originating from a primitive stem cell. "Mutations in the CBL gene are frequently detected in myeloid neoplasms and are associated with pathogenesis onset." (PMID 38643442, 2024). "Deletions or loss-of-function mutations in CBL are found in a wide range of myeloid malignancies, in particular, myelodysplastic syndrome/myeloproliferative neoplasm (MDS/MPN) overlap syndromes." (PMID 37317963, 2023). "CBL mutations have been identified in different myeloid neoplasms including MDS/MPN and acute leukemia but are rarely found in lymphoid malignancies." (PMID 38199781, 2023). "The findings in this work provide a potential mechanistic link between CBL/JAK2–mutated myeloid malignancies and activation of RAS signaling via upregulation of RAB27B." (PMID 37317963, 2023). "Our proteomic studies revealed RAB27B upregulation in CBL- or JAK2-mutated myeloid malignancies, and its expression correlated with poor prognosis in acute myeloid leukemias (AMLs)." (PMID 37317963, 2023). "The role of CBL as a cancer-predisposing gene was first identified in myeloid neoplasms, particularly in juvenile myelomonocytic leukemia (JMML)." (PMID 35159106, 2022). "Mutations in CBL have been observed in different types of myeloid malignancies accounting for ~5% of such cases." (PMID 33627783, 2021). "Further, patients with myeloid neoplasms having CBL mutations generally have a poor prognosis and so novel therapeutic strategies are urgently needed." (PMID 32015510, 2020). "Mutations in the E3 ubiquitin ligase CBL, found in several myeloid neoplasms, lead to decreased ubiquitin ligase activity." (PMID 31943762, 2020). "Activating mutations of CBL, a negative regulator of receptor tyrosine kinases, including the p.L380P detected in this case, is recurrent in myeloid malignancies and is associated with progression of MDS to AML." (PMID 29682367, 2018). "Clinically, it is important that c-CBL is mutated in a subset of patients who develop myeloid malignancies, which are diseases of the hematopoietic stem or progenitor cells." (PMID 32110709, 2017). "Conversely, CBL is regarded as a proto-oncogene with numerous mutations and important roles in some cancers, including myeloid neoplasms, colorectal cancer and glioma." (PMID 27842510, 2016). "Mutations causing alteration in the structure of CBL protein have recently been associated with various myeloid malignancies, including JMML." (PMID 26316488, 2015). "Tyr371 of the LHR in c-CBL has emerged as one of the most frequently mutated residues found in people with myeloid neoplasms." (PMID 23734257, 2013). "In the last few years, mutations in the CBL gene have been identified in a subset of human patients with myeloid malignancies." (PMID 21422499, 2011). "It is in this context that recent identification of mutations in CBL in a small but significant proportion of patients with myeloid malignancies provides an important milestone." (PMID 21422499, 2011). "Mutations in c-CBL have been recently reported in juvenile myelomonocytic leukemia and myeloid malignancies." (PMID 20126411, 2010). "Patients heterozygous for germline CBL loss-of-function (LOF) variants can develop myeloid malignancy, autoinflammation, or both, if some or all of their leukocytes become homozygous for these variants through somatic loss of heterozygosity (LOH) via uniparental isodisomy." (PMID 39403923, 2024). "In contrast to other myeloid neoplasms in which the impact of CBL mutations remains unclear, their presence in SM has been associated with poorer outcomes." (PMID 35626091, 2022). "Homozygous mutations in CBL have been found in a wide variety of myeloid neoplasms other than JMML." (PMID 35159106, 2022). "Patients with myeloid neoplasms having mutations in CBL generally have a poor prognosis." (PMID 31943762, 2020).
myeloid neoplasm (continued). "The co-occurrence of U2AF1 and signaling gene mutations also differed across myeloid neoplasms, with NRAS and FLT3 mutations being more common with S34 mutations and CBL, PTPN11 and CSF3R mutations more common with R156/Q157 mutations." (PMID 40386435, 2025). "Ren and colleagues have discovered a role of the CBL/JAK2/RAB27B/ZDHHC9 signaling axis in regulating NRAS trafficking to the plasma membrane for activation by palmitoylation in myeloid malignancies." (PMID 37317974, 2023). "CBL mutations or deletions within the LHR and RING domain have been identified in a substantial fraction of different types of myeloid malignancies." (PMID 33627783, 2021). "JAK inhibitors are effective in treating CBL or JAK2 mutated myeloid malignancies, but they are not curative." (PMID 37317963, 2023). "Moreover, the majority of CBL mutations in myeloid neoplasms have been reported in the absence of RAS or PTPN11 mutations, highlighting the mutual exclusivity of CBL mutations and other RAS pathway alterations." (PMID 35159106, 2022). "We previously reported that protein ubiquitination by CBL and CBL-B controls JAK2 stability and activity that is important for curbing hematopoietic stem and progenitor cell (HSPC) expansion and myeloid malignancies." (PMID 37317963, 2023). "Our observations of RAS pathway co-alterations (CBL and KRAS) in the EPI6 signature aligns with the documented activation of this pathway in CUX1-altered MNs, as recently demonstrated in the context of 7q alterations in myeloid neoplasms." (PMID 38890297, 2024). "Hence, this work reveals what we believe to be new signaling dynamics that enhance our understanding of compartmentalized RAS signaling, suggesting RAB27B as a therapeutic target to abrogate oncogenic CBL/JAK2 and RAS-driven myeloid malignancies." (PMID 37317963, 2023). "Despite somatic mutations in CBL being found in approximately 5% of myeloid neoplasms, leukemia other than JMML have not been reported frequently in patients with germline CBL mutations." (PMID 35159106, 2022). "Hence, we believe that this work uncovered a new signaling dynamic that enhances our understanding of compartmentalized RAS signaling, suggesting that targeting RAB27B may be therapeutically useful in oncogenic CBL/JAK2 and RAS driven myeloid malignancies." (PMID 37317963, 2023). "Previous research from Dr. Wei Tong’s laboratory has shown that ubiquitination of JAK2 by CBL and CBL-B regulates the stability and activity of the JAK2 protein, playing a critical role in curbing HSPC expansion and preventing the development of myeloid malignancies." (PMID 37317974, 2023).
juvenile myelomonocytic leukemia (25 papers, 2010 to 2025). A myelodysplastic/myeloproliferative neoplasm of childhood that is characterized by proliferation principally of the granulocytic and monocytic lineages. "The RING-type E3 ligase Casitas B-lineage lymphoma (CBL) is also found to be mutated in Noonan syndrome-like disorder, as well as early-onset juvenile myelomonocytic leukemia (JMML)." (PMID 32344852, 2020). "CBL is a proto‐oncogene with mutations identified in juvenile myelomonocytic leukemia and acute lymphoblastic leukemia, as well as Noonan syndrome." (PMID 32894644, 2020). "Sporadic and germline c-CBL mutations have been yet identified in JMML (Juvenile Myelomonocytic Leukemia) patients with the emerging of Y371H mutation, which results in the loss of Cbl’s ubiquitin ligase function." (PMID 30181811, 2018). "Mutations of CBL, often genetically-inherited, are particularly common in Juvenile Myelomonocytic Leukemia (JMML), a disease that manifests early in children." (PMID 27449297, 2016). "Missense mutations in CBL (Cbl proto-oncogene, E3 ubiquitin protein ligase) cause impaired growth, developmental delay, cryptorchidism and predisposition to juvenile myelomonocytic leukemia." (PMID 25306138, 2014). "In this study, one patient harbored a CBL variant, with the disease phenotype presenting as juvenile myelomonocytic leukemia (JMML)." (PMID 41477271, 2025). "The newly described CBL mutation-associated syndrome has been recently reported to show germline mutations in the Casitas B-lineage lymphoma proto-oncogene that resemble the Noonan syndrome phenotype and predispose a patient to juvenile myelomonocytic leukemia." (PMID 35887217, 2022). "Phenotypically related to pCMML, juvenile myelomonocytic leukemia (JMML) is a pediatric neoplasm often initiated by germline (CBL, NF1, PTPN11) or somatic (NRAS, KRAS, CBL, RRAS) RAS-activating mutations and is described as a bona fide RASopathy26,27." (PMID 34006870, 2021). "CBL variants have been associated with Noonan-like disorder with or without juvenile myelomonocytic leukemia (NSLL, MIM# 613563) also known as CBL syndrome." (PMID 40913078, 2025). "Clinical features of patients with germline c-CBL (Casitas B-lineage Lymphoma) mutations partially overlap those of NS, including developmental delays, growth defects, facial dysmorphia, and a predisposition to hematological malignancies, specifically juvenile myelomonocytic leukemia (JMML)." (PMID 33987182, 2021). "Juvenile myelomonocytic leukemia (JMML) is a rare pediatric MDS/MPN overlap syndrome that is characterized by somatic mutations in NF1, CBL, NRAS, KRAS or PTPN11 that result in the activation of RAS/MAPK or JAK/STAT signaling." (PMID 31171568, 2019).
leukemia (25 papers, 2009 to 2024). A malignant (clonal) hematologic disorder, involving hematopoietic stem cells and characterized by the presence of primitive or atypical myeloid or lymphoid cells in the bone marrow and the blood. "We aimed to compare the molecular consequences of the CBL variants with a high frequency in the general population with those of variants reported in patients with leukemia, NS, and the Y371C variant present in P1, P2, and P3." (PMID 39403923, 2024). "Somatic leukemia cells presented with homozygous CBL mutations resulting from copy-neutral LOH and an additional chromosomal gain at 11q." (PMID 35159106, 2022). "CBL is a proto-oncogene, and it is indicated that CBL is associated with the development of leukemia." (PMID 30930932, 2019). "The loss of c-CBL function in individuals with leukemia and myelodysplastic syndrome supports the potential therapeutic value of wild type c-CBL therapy in some hematologic malignancies, in addition to those with lung cancer." (PMID 27472394, 2016). "Nonetheless, our data are consistent with the notion that RAB27B plays a critical role in leukemia cell growth when NRAS is required — such as in AMLs with oncogenic NRAS or CBL mutations — while it is dispensable for the growth of AMLs with other dominant mutations or in normal HSPCs." (PMID 37317963, 2023). "However, mutations of CBL are associated with human leukemias, pointing to tumor suppressor roles of CBL proteins; hence, it is critical to assess the tumor-intrinsic roles of CBL and CBL-B in cancers." (PMID 27276677, 2016). "Notably, RAB27B was important for the growth of leukemia cells with CBL or NRAS mutations." (PMID 37317963, 2023). "All three 11q22.3 deletions involving ATM (sizes: 16, 17, and 18 Mb) also encompassed at least two of the other nearby leukemia-associated genes (BIRC3, ZBTB16, KMT2A, or CBL)." (PMID 36831635, 2023). "Here, we show that targeted SYK inhibition similarly enhances the effects of midostaurin and other FLT3 inhibitors against mutant CBL‐positive leukaemia." (PMID 31943762, 2020). "We show that FLT3 inhibitors ranging from promiscuous to highly targeted are potent inhibitors of growth of leukaemia cells expressing mutant CBL in vitro, and we demonstrate in vivo efficacy of midostaurin using mouse models of mutant CBL." (PMID 31943762, 2020). "The truncated CBL protein vCBL lacks a RF domain and can induce leukemia and lymphoma in mice." (PMID 37741817, 2023). "In addition, conditional knock-in mice expressing CMML-associated CBL-Q367P or ligase-dead CBL-C379A mutant developed CMML-like phenotypes and leukemia, respectively." (PMID 33627783, 2021). "Therefore, it would be expected that targeted inhibitors of FLT3 would be an effective therapy for CBL mutant‐driven leukaemia as well as for mutant FLT3‐positive leukaemia." (PMID 31943762, 2020). "Future studies should examine the kinetics of receptor turnover and phosphorylation peak and attenuation in this primary population, the signaling pathways involved and determine whether CD116 can be used to distinguish between CBL mutant leukemia vs. healthy stem cells." (PMID 39298477, 2024). "No such effect is observed when CBL UbLOF variants are expressed in hematopoietic stem cells from WT mice, a situation reminiscent of that in humans heterozygous for germline CBL UbLOF variants, who do not develop leukemia until LOH occurs." (PMID 39403923, 2024). "Notably, RAB27B is important for the growth of leukemia cells with CBL or NRAS mutations but does not affect normal hematopoiesis." (PMID 37317963, 2023). "CBL mutations are frequent in chronic myelomonocytic leukemia (5–13% of patients) and acute myeloid leukemia (AML), particularly forms secondary to myelodysplastic syndromes (9% of cases), suggesting that CBL mutations may contribute to leukemia development." (PMID 35159106, 2022).
leukemia (continued). "Taken together, our findings suggest that FLT3 inhibitors in advanced stages of development or FDA approved as therapy for mutant FLT3‐positive AML, and representing a wide range of specificity for FLT3, could similarly be considered as treatments for mutant CBL‐positive leukaemia." (PMID 31943762, 2020). "Moreover, CBL restricts myeloid proliferation of human AML1-ETO-induced leukemia." (PMID 33231565, 2020). "Although in vitro studies demonstrated that expression of CBL exon 8 and/or exon 9 deletions in a CBL wild-type context shows a transforming phenotype, in the AML patients this alteration was found only in concomitance with other aberrations, particularly CBF leukemia." (PMID 35159106, 2022).
acute myeloid leukemia (21 papers, 2010 to 2025). Acute myeloid leukemia (AML) is a group of neoplasms arising from precursor cells committed to the myeloid cell-line differentiation. "Somatic CBL mutations have been reported in a variety of malignancies, ranging from acute myeloid leukemia to lung cancer." (PMID 35159106, 2022). "CBL mutations play a crucial role in many cancers, including acute myeloid leukemia." (PMID 33954256, 2021). "Recently, the first human c-CBL mutations were reported in acute myeloid leukemia (AML) patients." (PMID 20126411, 2010). "RAB27B overexpression in myeloid malignancies with CBL or JAK2 mutations correlates with poor acute myeloid leukemia (AML) prognosis." (PMID 40977744, 2025). "In 2007, two groups simultaneously identified CBL mutations in acute myeloid leukemia (AML) patient samples." (PMID 21422499, 2011). "KMT2A::CBL is a rare fusion of unknown pathogenesis generated by a unique interstitial deletion of chromosome 11 that has been reported across a wide age range in both acute myeloid leukemia (AML) and acute lymphoblastic leukemia (ALL) patients." (PMID 38643442, 2024). "In human acute myeloid leukemia (AML), transformation by mutant CBL depends on functional expression of Cdc42 and increased glucose metabolism." (PMID 30621321, 2019). "In acute myeloid leukemia (AML), UBASH3B is upregulated by AML1-ETO fusion protein to promote the growth of AML cells by functionally regulating CBL." (PMID 32010618, 2019). "In Acute Myeloid Leukemia (AML) induced by the oncogene AML-ETO, UBASH3B inactivates CBL, which is predicted to inhibit the ubiquitination of its downstream effectors responsible for leukemogenesis." (PMID 38461240, 2024). "The activity of CBL, the main E3 ligase responsible for the regulation of turnover for RTKs, is targeted through a disordered linker/autoregulatory region in acute myeloid leukemia (AML) and other hematopoietic disorders." (PMID 33806614, 2021). "In acute myeloid leukemia (AML), UBASH3B contributes to myeloid proliferation and leukemogenesis through CBL inactivation and AML1-ETO-induced signaling." (PMID 40885971, 2025). "Of note, mutations in several of the genes that confer leukemia predisposition (e.g., CEBPA, ETV6, GATA2, NF1, RUNX1, PTPN11, CBL, and RAS) are also frequently found in sporadic acute myeloid leukemia (AML) or myelodysplastic syndrome (MDS)." (PMID 29326930, 2017).
Noonan syndrome (21 papers, 2013 to 2025). Noonan Syndrome (NS) is characterized by short stature, typical facial dysmorphism and congenital heart defects. "Mutations associated with Noonan syndrome alone include CBL, BRAF, KRAS, LZTR1, MAP2K1 (MEK1), NRAS, PTPN11, RAF1, RIT1, SOS1 and SOS2." (PMID 38550930, 2023). "The study included 137 patients (Noonan syndrome, n=119; Noonan syndrome with multiple lentigines, n=4, Noonan-like syndrome with loose anagen hair, n=4, and CBL-mutation associated syndrome n=10)." (PMID 31475511, 2020). "Four of the proteins are linked to various forms of the Noonan syndrome (CBL, MAP2K1, RAF1 and SOS), 5 to various types of tumors (MAPK1, PRKCQ, ABL1, GRAP2 and RAS) and one to an autoimmune disorder (RASGRP1)." (PMID 28448599, 2017). "In addition to the PTPN11 mutations in the RAS‐MAPK signaling pathway, including KRAS, SOS1, RAF1, SHOC2, NRAS, BRAF and CBL, can also cause Noonan syndrome." (PMID 37525886, 2023). "When considering only cases informative for outcome after HSCT and excluding patients with Noonan syndrome, CBL mutation or incomplete mutational analysis (n = 92), OS still tended to be inferior in the HM group, but the comparison failed to reach statistical significance." (PMID 29259247, 2017). "Other rarer mutations, leading to the development of Noonan Syndrome, have been observed in the BRAF, SHOC2, and CBL genes." (PMID 36982349, 2023). "Our patient carried a somatic CBL mutation (NM_005188.3 c.1186T>C) described once previously as germline pathogenic in JMML and Noonan-like syndrome." (PMID 37833906, 2023). "Noonan Syndrome is due to germline pathogenic variants involving genes such as PTPN11, SOS1, KRAS, NRAS, SHOC2, CBL and MAP2K1." (PMID 36982349, 2023). "Clinical features overlap with Noonan syndrome and type 1 neurofibromatosis, suggesting the important role of the CBL gene in regulating the RAS pathway, which is essential to the orchestration of the developmental program of many species." (PMID 35887217, 2022). "In addition, we verified by exomeanalysis that the patient did not have any pathogenic variants in the genes associatedwith Noonan Syndrome and other rasopathies (PTPN11,SHOC2, KRAS, CBL,SOS1, RAF1, HRAS,NRAS, RASA1, SPRED1,BRAF, MAP2K1, MAP2K2, RIT1 andRRAS)." (PMID 27561113, 2016). "It has been demonstrated that pathogenic germline variants in the CBL gene impact the ubiquitylation and migration of EGFR, resulting in loss of downregulation function of the CBL protein in the RAS-MAPK pathway, which leads to Noonan syndrome and other RASopathies." (PMID 37711606, 2023).